RN7SKP49 (RN7SK pseudogene 49)
Gene: Miscellaneous RNA gene on chromosome 1 (224,107,282 to 224,107,541, reverse strand). Ensembl gene ENSG00000252484.
Homologues: Orthologues: chimpanzee 7SK (99% identical). Paralogues in human: RN7SKP222 (58% identical), RN7SKP161 (58% identical), RN7SKP181 (57% identical), RN7SKP151 (56% identical), RN7SKP202 (56% identical), RN7SKP103 (55% identical), RN7SKP226 (55% identical), RN7SKP47 (55% identical), RN7SKP6 (55% identical), RN7SKP69 (55% identical), RN7SKP128 (55% identical), RN7SKP203 (55% identical), and 284 more.